FAP (fibroblast activation protein alpha)
Diseases named in the same sentence as FAP in open-access papers (continued):
Sharing a sentence is not in itself a finding about the gene and the disease.
tumor (continued). "Shortly afterward, a compound directly related to FAP-2286 called 3BP-3940 was studied in clinical settings and also displayed excellent properties as a molecular PET imaging agent, including a remarkably high tumor-to-background ratio and minimal renal accumulation." (PMID 40766056, 2025). "At the same time, FAP-targeted therapy does not guarantee the elimination of CAFs that are detrimental to tumor progression, and it may also eliminate CAFs that inhibit tumor growth." (PMID 40248695, 2025). "Specifically, in FOXL2+COL1A1− cells, we examined expression of other AGCT tumor markers such as SF1, calretinin, and inhibinα, whereas in FOXL2+COL1A1+ cells, we also examined expression of stromal markers, including αSMA, vimentin, S100A4, PDGFRa, PDGFRb, and FAP." (PMID 41042551, 2025). "Notably, genes such as FAP, SERPINH1, and PSAPL1 have emerged as promising biomarker candidates due to their significant upregulation in GC tissues and their functional relevance in tumor progression, extracellular matrix remodeling, and immune evasion." (PMID 41244835, 2025). "Other authors have shown markers like fibroblast activation protein (FAP) for the possible evidence of activity of CAF in OSCC that may help guide treatment aimed at altering the interactions between stromal tissue and the tumor." (PMID 40881676, 2025). "This raises the possibility that some FAP + cells identified in our analysis could originate from the tumor itself rather than from the stromal compartment." (PMID 39751643, 2025). "This study evaluated one FAP-negative xenograft model (HCT116) as a specificity control; additional FAP-negative models could further confirm tracer selectivity across tumor types." (PMID 41460404, 2025). "Therefore, while anti-PD-1 treatment showed partial tumor inhibition, the absence of a FAP+CAF-free group limits our ability to definitively attribute reduced immunotherapy efficacy to FAP+CAF-mediated resistance." (PMID 40843362, 2025). "Following 177Lu labeling, SPECT results demonstrated optimal tumor uptake and biodistribution of 177Lu-FAPI-46-EB in the high FAP-expressing HT1080.hFAP model, whereas showing poor tumor uptake and biodistribution in the moderately FAP-expressing HEK293.hFAP model." (PMID 40438601, 2025). "Since FAP is overexpressed in the tumor microenvironment and is generally absent from other tissues in healthy adults, some research groups have focused on utilizing FAP protease activity to selectively activate prodrugs at the tumor sites to enhance drug efficacy and reduce toxicity." (PMID 41373408, 2025). "Promising strategies have emerged, including FAP-activated prodrugs that selectively target tumour stroma, inhibition of specific signalling pathways involved in CAF-cancer cell crosstalk, and repurposing existing drugs like losartan for modulating the tumour microenvironment." (PMID 40741380, 2025). "However, using a backward stepwise (Wald) method, FAP expression did not retain independent prognostic value, whereas age, tumor grade, and pT stage remained statistically significant predictors of disease-free survival." (PMID 41303595, 2025). "Compared with the rapid tumor progression observed in untreated (Utd) mice, tumors in FAP/IL-15 CAR-T-treated mice exhibited minimal or no growth, suggesting enhanced antitumor activity via precise targeting of FAP-positive cells and IL-15 secretion by effector cells." (PMID 41455698, 2025). "FAP positive CAF were also not found to increase tumour progression or recurrence in mouse models." (PMID 40741380, 2025). "Meantime, we found that OHSV2-DSTEFAP/CD3-based therapy exhibits the absence of off-tumor toxicity, including cytokine storm, inconsistent with previous studies on FAP targeting therapy and CAR-T therapy, despite GPC3 and FAP are suboptimal targets owing to their low specificity." (PMID 40406146, 2025).
tumor (continued). "According to the existing literature review, we could not find any literature on a pan-cancer analysis of FAP from a whole-tumor perspective." (PMID 39055892, 2024). "Similarly, [68Ga]-FAPI-46 had a similar uptake in the tumor to FAP-2286, but FAPI-46 exhibited a faster clearance in the background tissue, providing an improved tumor-to-background ratio of 3–5 times more than that of FAP-2286 at early time points." (PMID 39065684, 2024). "Eight tumor tissues and four normal tissues were negative in terms of FAP expression, and 84 tumor tissues and 15 normal tissues expressed the FAP marker, of which 72 tumor tissues and 1 normal tissue showed a high level of expression of the FAP marker at the surface of CAFs." (PMID 39030445, 2024). "In our human xenograft models, FAP-CAR T cells did not lose activity in the NCG tumor microenvironment, suggesting that through elimination of FAP-positive stroma cells could FAP-CAR T cells limit the tumor growth." (PMID 39086477, 2024). "Also as expected, the viability of FAP− tumor cells cultured alone was not affected by incubation with FAP‐CAR‐T cells, thereby ruling out off‐target effects." (PMID 38975278, 2024). "In addition to confirming the specificity and activity of FAP‐CAR‐T cells, we also uncovered a potent bystander killing mechanism that could facilitate more complete tumor destruction than would be predicted by antigen expression alone." (PMID 38975278, 2024). "The cross reactivity of FAP-CAR T cells brings us convenience to somewhat investigate the contributions of CAFs ablation to tumor progression in allografted mice models, and need not to use conventional xenograft mouse models in which human cancer cells with human CAFs are co-injected." (PMID 39086477, 2024). "Next, it was determined whether the in vivo FAP expression differs from the in vitro expression for the three tumor cell lines, including HT1080-WT as a negative control." (PMID 39718718, 2024). "Thus, FAP‐CAR‐T cells can exert substantial bystander killing of tumor cells lacking FAP, but only once they have been activated by cells expressing their cognate antigen." (PMID 38975278, 2024). "Furthermore, our analyses and previous reports have highlighted the limited or absent expression of FAP in normal, non-malignant tissues, contrasting with its abundance in tumor stroma and pericytes of tumor neovasculature." (PMID 38558814, 2024). "However, inflammation, bone degeneration, scars, and healing areas can also express FAP and cause non-specific FAPI accumulation during tumor detection." (PMID 39595051, 2024). "Additionally, the staining intensity of FAP and DAB2 also exhibited a significant positive correlation with tumor size and patient serum AFP concentration (Spearman correlation analysis, P < 0.0001), suggesting their potential as indicators of tumor progression in clinical practice." (PMID 39239526, 2024). "We suspected that the longer blood retention could be caused by the increased lipophilicity of the ligands and potential interactions, such as π–π stacking between the quinoline ring and anthracene ring, which hindered the binding of tracers to FAP and PSMA, leading to decreased tumor uptake." (PMID 38398552, 2024). "Because of these and other functions, CAFs have been historically labeled as tumor-promoting cells; however, therapeutic targeting of the αSMA+ CAFs has not demonstrated significant benefits in inhibiting tumor growth, while FAP targeting strategies such as the use of CAR-T have been inconclusive." (PMID 38509063, 2024). "Tumor uptake was high and not depending on FAP expression in TME." (PMID 38575990, 2024). "Notably, we found that the FAP+ fibroblasts secreted CCN2, previously reported as a coactivator of the TGF-β pathway via direct binding to TGF-β, cooperating with TGF-β to activate the pathway, thus promoting the transition of tumor cells into the EMT-subtype." (PMID 39095854, 2024).
tumor (continued). "The anti-FAP CAR-T cells effectively eliminated stromal cells and depleted the immunosuppressive matrix, and subsequent treatment with anti-MSLN CAR-T cells led to improved tumor control, suggesting that stromal depletion sensitized the tumor to treatment with the anti-MSLN CAR-T cells." (PMID 39796666, 2024). "Moreover, [68Ga]Ga-FAP-2286 demonstrated a higher SUVmax of 11.1 compared to 6.9 for [18F]FDG and a median tumor-to-background ratio of 9.2 compared to 3.0 for [18F]FDG, indicating superior tumor lesion detectability." (PMID 39765634, 2024). "Taken together, FAP+ fibroblasts and SPP1+ macrophages coordinated to remodel ECM and promoted connective tissue proliferation, preventing the infiltration of lymphocytes into the tumor core and thereby reducing the efficacy of programmed death-ligand 1 (PD-L1) blockade immunotherapy." (PMID 39858416, 2024). "Antibody-based FAP-targeted radiopharmaceuticals like [89Zr]Zr/[177Lu]Lu-AMS002-1-Fc rAb and FAP inhibitor (FAPI) radiopharmaceuticals such as [211At]At/[225Ac]Ac-FAPI-04 and [177Lu]Lu/[225Ac]Ac-FAPI-46 have demonstrated tumor growth suppression in preclinical models 45-47." (PMID 38646648, 2024). "Interestingly, Pearson coefficients showed that the degree of correlation between tumor SUVmax of 68Ga-FAPI and tumor-infiltrated CD8+ or CD4+ cells was comparable to the correlation between SUVmax of 68Ga-FAPI PET/CT and the expression of FAP-α." (PMID 38175716, 2024). "Our FAP‐CAR‐T cell products contain ~75% CAR‐negative T cells, leading us to hypothesise that CAR‐T cells may secrete cytokines to mobilise the non‐transduced T cells into the antitumor response after activation by FAP‐expressing tumor cells." (PMID 38975278, 2024). "Given the described role of FAP+ CAFs in regulating desmoplastic reaction and CD44+ macrophages as highly phagocytic cells, in an attempt to speculate these cells can cooperate to a ECM remodeling niche that promotes tumor cell invasion and PDAC progression." (PMID 39575252, 2024). "Therefore, we hypothesized that the combination of FAP-targeted RPT and CXCR4 antagonist would effectively treat TNBC by direct tumor killing and TME reprogramming." (PMID 38587644, 2024). "The AUC of the tumor uptake and absorbed dose was higher for [177Lu]Lu-FAPI-46-F1D and the two albumin binder conjugates, [177Lu]Lu-FAPI-46-Ibu and [177Lu]Lu-FAPI-46-EB, in HT1080.hFAP xenografts and for [177Lu]Lu-FAPI-46-EB and [177Lu]Lu-FAP-2286 in HEK293.hFAP xenografts." (PMID 37261473, 2023). "The dual CAR T approach also imposes that quantity of FAP-targeting cells be the same as the quantity of tumor-targeting cells although the two CARs might not have the same therapeutic window." (PMID 37251405, 2023). "At the same time, depletion in growth factors associated with a decrease in FAP expression provides wide opportunities for identifying individual factors that are important for FAP expression, but are not required for adult tissues, which can be used for tumor-specific ligand-receptor targeting." (PMID 37509656, 2023). "The effect of FAP in tumor immune system was not investigated until recent years." (PMID 37325617, 2023). "Within the CRC cohort, expression of FAP did not correlate with tumor stage or grading." (PMID 37614665, 2023). "Therefore, to address if the changes in the TME induced by the combination of FAP- and Meso-CAR T might have the potential to engage endogenous anti-tumor immunity, 4662 tumor-bearing C57BL/6 were pre-treated with MigR control or FAP-CAR T cells." (PMID 37607999, 2023). "We then investigated the associations of arterial wall uptake with calcified plaque burden (including number of plaques, plaque thickness, and calcification circumference), CVRFs, FAP-positive total tumor burden, and image noise (coefficient of variation, from normal liver parenchyma)." (PMID 37147478, 2023).
tumor (continued). "The absence of cell proliferation changes with FAP-α overexpression in 231-FAP cells are consistent with previous studies that showed that FAP-α overexpression in MDA-MB-231 cells increased tumor growth and vascularization without increasing cell proliferation." (PMID 36937451, 2023). "Considering FAP is overexpressed mainly in CAFs and not in tumor cells, FAPI-PET may not always reflect the actual tumor microenvironment." (PMID 39355017, 2023). "Bispecific antibodies of FAP and IL-2 receptor (RO6874281) or 1BBL (RG7826) are being tested in combination with ICBs on clinical trials and have shown to be safe, and preclinical models encourage the advancement due to promising results such as tumor regression, accumulation of CD8+ T and NK cells." (PMID 37284199, 2023). "High ADH1B but low FAP expression after neoadjuvant treatment might indicate the main contribution of ADH1B + CAF to fibroblasts, potentially enhancing anti-tumor immune activity." (PMID 37537219, 2023). "They reported increased FAP expression in the center of the tumor as a negative prognostic factor." (PMID 37316886, 2023). "In cancers of epithelial origin, FAP expression is mainly restricted to the CAFs in the TME, which possesses diverse roles in cancer biology, such as stromatogenesis, reciprocal signaling interactions with cancer cells, and immune suppression through crosstalk with tumor-infiltrating leukocytes." (PMID 37086273, 2023). "The interaction between FAP+ fibroblasts and SPP1+ macrophages contribute to the formation of a desmoplastic TME, which hinders lymphocyte infiltration and may lead to resistance to tumor immunotherapy." (PMID 38187388, 2023). "Staining done 7 days post-T cell injection showed the tumors to be devoid of GFP+ CAR T cell infiltration in mice treated with MigR control and Meso-CAR T cells which notably had no impact on either FAP+ stromal cell or Mesothelin+ tumor cells even by day 7 post-T cell administration." (PMID 37607999, 2023). "On the contrary, the expression of FAP, a molecule involved in epithelial-to-mesenchymal transition and tumor invasion, was unvarying after both EV-CTR and EV-ASA treatment, showing the activation or reduction of a selective pathway mediated by tumor-derived EV." (PMID 37569393, 2023). "Therefore, we conclude that in vivo tumor margin delineation would still be feasible irrespective of peritumoral inflammatory reactions using an anti-FAP targeting NIR tracer." (PMID 37727209, 2023). "Taking into consideration these observations, FAP might not qualify as a suitable target in scar excision or revision of incomplete tumor resection shortly after the initial surgery due to the presence of activated fibroblasts in the healing wound." (PMID 37727209, 2023). ", which indicated that high FAP expression at the invasive margin positively correlates with the tumor stage; however, there is no such correlation regarding high FAP expression in the tumor center." (PMID 37316886, 2023). "Thus, given the fibroblastic and myofibroblastic proliferations that characterize these tumors, it is not surprising that these tumor types show intense FAP expression." (PMID 37333052, 2023). "While Meso UCAR or FAP(hF1) UCAR T-cell treatment alone did not affect tumor growth, relative to UT-cell control, FAP(hF1) UCAR T-cells pre-treatment with subsequent Meso UCAR T-cell administration significantly decreased tumor size, relative to all other treatment groups." (PMID 37251405, 2023). "Thus, radioligand therapy (RLT) with [177Lu]Lu-DOTA-FD3 has a good therapeutic effect in stroma-rich tumors despite negative FAP expression on the tumor cells." (PMID 38706713, 2023). "The uptake of various tracers targeting FAP-labeled fibroblast-activating protein inhibitors (FAPI) is high in most tumors but low in normal tissues, such as in the brain and abdomen, resulting in a good tumor-to-background ratio (TBR) and good tumor delineation." (PMID 36675506, 2023).
tumor (continued). "In most solid tumors, the mechanism of action of TRT targeting FAP is to damage CAFs in the stroma surrounding tumor cells, as well as cross-fire effect to kill some tumor cells, but does not have a direct targeted killing effect on all tumor cells." (PMID 38706713, 2023). "The uptake values in FAP-expressing HEK293T:hFAP tumor xenografts were 2.99 ± 0.37, 3.69 ± 0.81, 3.64 ± 0.83 %ID/g for [68Ga]Ga-AV01017, [68Ga]Ga-AV01030, and [68Ga]Ga-AV01038, respectively, which were also lower than the monospecific FAP-targeting tracer, [68Ga]Ga-FAPI-04 (12.5 ± 2.00 %ID/g)." (PMID 36770755, 2023). "These albumin binders could be used to fine-tune the blood residence time of pyridine-based FAP-targeted radioligands to maximize tumor uptake without inducing significant hematological toxicity." (PMID 36986548, 2023). "Results showed that the medium from FAP-over-expressed LX2 cells could significantly promote the motility of MHCC97H and SK-Hep1 LIHC cells, increase the invasion of THP-1 macrophages and induce them into pro-tumor M2 phenotype." (PMID 37325617, 2023). "However, four tumor markers (POSTN, pSMAD2/3, CXCL14, ADH1B, FAP) that have previously been reported to predict suboptimal debulking were selected in our model, although only p-SMAD2/3 was in the same direction but with lower discriminatory performance compared to prior reports." (PMID 36761962, 2023). "Available evidence has demonstrated that FAP plays a critical role in the formation of TME, in which this cell surface protease can shape key features of CAFs through proteome and degradome alterations to suppress antitumor immunity and facilitate tumor growth and metastasis." (PMID 37773704, 2023). "Therefore, 68Ga-FAPI-46 shows high metabolic uptake in tumor tissues, which can reflect the expression quantity of FAP in tumor lesions and provides a new means and method for non-invasive imaging and targeted FAP therapy of solid tumors." (PMID 36675506, 2023). "In cases where there is incongruity between the MRI findings and clinical symptoms, the inclusion of a blood FAP test can serve as an indirect means of confirming the presence of tumor progression that may not be visually detectable." (PMID 37864148, 2023). "Thus, FAPα-dependent changes in ECM promote vascular and tumor cell invasion along the specific parallel orientation of collagen fibers, as evidenced by the increased targeting and velocity of cancer cells to the ECM from FAPα+ cells." (PMID 38136590, 2023). "Furthermore, our observations suggest that expression of FAP in healthy and peritumoral non-neoplastic tissues is limited to low levels, resulting in an adequate tumor-to-normal tissue ratio." (PMID 37727209, 2023). "However, the plasma concentration of FAP in non-tumor patients was not significantly different in patients with a variety of cancers." (PMID 36632455, 2023). "Moreover, a higher number of total T cells accumulated in tumor nests accompanied by significantly decreased expression of PanCK+ tumor cells and depletion of PDPN+ CAFs in the tumors treated with FAP-CAR T cells followed by FAP-CAR and Meso-CAR T cells than in other combinations." (PMID 37607999, 2023). "In addition, compared to Nb-BiTE or control group, Nb-TriTE induced higher GzmB and PRF1 secretion levels after incubation with FAP+ tumor cells, but no significant changes in FAP− HepG2 tumor cells." (PMID 38031188, 2023). "In human STS, we could not assess the impact of the tumor grade on the FAP expression statistically, as most of them were high grades." (PMID 37727209, 2023). "There is also a strong relationship between the presence of CAFs and tumor-infiltrating immune markers in various cancers, such as head and neck and lung cancer—for instance, the correlation between CAF and CD16-positive TAMs in α-SMA positive stained and CAFs marker FAP and CD14, respectively." (PMID 36139552, 2022). "The absence of FAPα+ CAFs cells appears to restore immune detection and tumour destruction." (PMID 36555218, 2022).